IL1B (interleukin 1 beta)
Diseases named in the same sentence as IL1B in open-access papers (continued):
Sharing a sentence is not in itself a finding about the gene and the disease.
tumor (continued). "The membrane-bound IL-1α exhibits a mainly immunostimulatory activity, while IL-1β in the TME exhibits a pro-inflammatory role in tumorigenesis and tumor-invasion-promoting activity, as well as immunosuppressive activity." (PMID 33557173, 2021). "Compared to healthy individuals, the NPC patients exhibited elevated levels of IL-1β, IL-2 and IL-10, which is in accordance with previous findings in patients with NPC and in tumor-bearing rodent models." (PMID 34900691, 2021). "This study showed NLRP3 in CAFs to mediate IL-1β-dependent recruitment of both CD11b+Ly6CloLy6G+ PMN-MDSCs and CD11b+Ly6ChiLy6G− monocytic MDSCs into the tumor bed depending on the genetic background of the tumor model." (PMID 34638239, 2021). "pSTAT3 is activated by various cytokines such as IL-6, IL-1b, IL-10, GM-CSF, and VEGF secreted mainly in the TME by tumor cells." (PMID 35011582, 2021). "The NK-exosome-treated tumor group showed a meaningful reduction in the expression of Bmi-1, MMP-3, IL-1β, IL-6, TNF-α, Bax, and Bcl-xL compared with the tumor group." (PMID 34527741, 2021). "In the inflammatory microenvironment of tumor, immune cells can release inflammatory factors such as TNF-α and IL-1β after immune cell infiltration, promote tumorigenesis, invasion and metastasis." (PMID 34120620, 2021). "IL-1β promotes cancer metastasis to bone by increasing EMT and tumor cell invasion and migration to the bone marrow and adipose tissue." (PMID 34064859, 2021). "ATP released from the dying tumour cells would bind to the P2X7R expressed on dendritic cells (DCs) to activate the inflammasome, allowing for the production of IL-1β and activation of CTLs." (PMID 33918087, 2021). "IL-1β and TNF-α have anti-tumor effects and can inhibit the growth and metastasis of tumors in vitro and in vivo." (PMID 34034714, 2021). "It was shown that IL-1β further induced CC- chemokine ligand 2 (CCL2) to amplify MDSC indirectly in macrophages and tumor cells." (PMID 34975496, 2021). "Inflammation often exists in the tumor microenvironment and is induced by inflammatory mediators such as TNF-α, IL-6, IL-1β." (PMID 33953676, 2021). "In the tumor stage contrasts for STAD and COAD, we see Th2 and NK cells expressing inflammation related genes IL1A, IL1B, IL4, and TNF." (PMID 34512714, 2021). "In a nude mouse xenograft tumor model, tumor developed from SW1990 and Panc-1 cells stimulated with IL-1β, TNF-α, and Shh was significantly promoted compared to control animals, whereas no stimulating effect was observed on tumor development from BxPC-3 cells." (PMID 34046348, 2021). "Some cytokines that are involved in inflammation response, including IL‐1β, IL‐6, TNF, and C‐reactive protein (CRP), are increased in depressed patients and promote tumor progression." (PMID 34723436, 2021). "In IECs, expression of STAT1 gene was also predicted to be upregulated by inflammatory cytokines IL1β and IFNγ and growth factor FGF7 identified as key molecules involved in tumor microenvironment." (PMID 34946170, 2021). "MDSCs interact with the TME, and tumor and stromal cells secrete TGF-β, MMP9, BV8, IL-6, IL-1β, β-FGF and VEFG through autocrine and paracrine mechanisms, mobilizing and expanding MDSCs and further promoting tumor growth." (PMID 34925375, 2021). "The expansion and activation of MDSCs in the TME are mainly induced by cytokines secreted by tumor cells or activated immune cells, such as VEGF, GM-CSF, M-CSF, G-CSF, IL-1β, IL-4, IL-6, and IFN-γ." (PMID 34527668, 2021). "Western blot assay was used to detect the expression levels of tumor progression and MDSC activation-related factors in the IL-1β/NF-κB pathway." (PMID 34055197, 2021). "Tumor cells directly stimulate osteoclastogenesis by expressing molecules such as RANKL, IL-6, IL-8, IL-11, IL-1, and IL-1B; they also indirectly stimulate osteoclastogenesis by increasing RANKL production in osteoblasts via PTHrP expression." (PMID 34257573, 2021).
tumor (continued). "MSCs can be activated within tumor microenvironments by the pro-inflammatory cytokines TNF-α, IFN-γ or IL-1β, which are secreted by macrophages and tumor cells." (PMID 33472580, 2021). "STAT3 and ERK are activated by common interleukins in a tumor microenvironment like IL-10, TNF-α, and IL1β." (PMID 34177892, 2021). "We observed significant changes in tumorigenesis-related markers including CD133, Bmi-1, VEGF, MMP-3, IL-1β, IL-6, TNF-α, and MDR in the tumor group compared with the control group." (PMID 34527741, 2021). "IL-1B ablation in the microenvironment removed this spatial bias, resulting in an equal number of iNOS+ and CD163+ macrophages in both areas of tumour viability and necrosis." (PMID 34290237, 2021). "The obese tumor microenvironment induced an increase in the number of tumor-infiltrating macrophages with an activated NLRC4 inflammasome, which further activated IL-1β." (PMID 33987528, 2021). "IL-1β neutralization promotes intratumoral CD8+ T cell infiltration and function and sensitizes PDA to immunotherapy, confirming that the effects of tumor cell-derived IL-1β are NLRP3-dependent and identifying a tumor-supportive role for NLRP3 in PC." (PMID 34064909, 2021). "Among the cytokines that correlate with CD68+ macrophages, IL-1β, IL-13 and VEGF have previously been described as tumor promoting factors." (PMID 34654395, 2021). "In contrast, in the syngeneic tumor cell engraftment system, elevated cytokine expression of IL-1β, IL-6, IL-2 and IFN-γ in GABARAP KO immune cells probably inhibited tumor cell growth." (PMID 34502326, 2021). "DCs are recruited to infected tumors following S. Typhimurium administration, and those isolated from the tumor‐draining LNs produced more IL‐6, TNF‐α, and IL‐1β than DCs harvested from control mice." (PMID 34633664, 2021). "By contrast, the NK-exosome-treated tumor group exhibited a significant reduction in Bmi-1, MMP-3, IL-1β, IL-6, TNF-α, Bax, Bcl-xL, and PCNA expression compared with that in the tumor group." (PMID 34527741, 2021). "Pro-tumorigenic role: TLR is able to send its pro-tumorigenic signals in tumor cells or in TME by enhancing NF-kB, which, in turn, activates its cascade made up of IL-1β, TNF-α, IL-6." (PMID 34944856, 2021). "These macrophages secrete proinflammatory factors such as IL-6, IL-12, IL-1β, and TNF-α and highly express MHC class I and MHC class II molecules that recognize tumor-specific antigens." (PMID 34335093, 2021). "M1 macrophages possess antitumor activities by producing pro-inflammatory cytokines, such as IL-1β, IL-6, and TNF-α, while M2 macrophages possess pro-tumor activities by producing anti-inflammatory cytokines, such as IL-10, IL-13, and TGF-β." (PMID 33230600, 2021). "In models of dormancy, IL-1β together with TNF-α stimulated the reactivation and proliferation of tumor cells within an osteoblastic matrix." (PMID 34064859, 2021). "The proinflammatory cytokine IL-6 is released by various immune cells triggered by IL-1β and TNF, but also produced by tumor cells directly as also proven for MPM with tumor-promoting effects." (PMID 33562138, 2021). "Diet-induced obesity results in increased tumor burden in mice, by prompting increased NLRC4-dependent production of IL-1β from tumor-infiltrating macrophages." (PMID 35111698, 2021). "Densitometry analysis showed that five cytokines, IL-4, AXL, IL-1β, IL-9, Exotaxine-2 and IL2, were upregulated, and two cytokines, PF4 and IL-6, were downregulated in the tumor environment of JEG3-Sh-NLRP7 cells." (PMID 34203890, 2021). "However, our previously published data, using T cell deficient mice, have demonstrated that inhibiting IL-1B or IL1R signalling can both hold disseminated tumour cells in a dormant state in bone preventing metastatic outgrowth and slow down growth of established tumours in bone." (PMID 34290237, 2021).
tumor (continued). "Additionally, the HIFU-induced upregulation of the genes Il6 and Il1β, which the authors hypothesized could promote a chronic inflammatory pro-tumor environment, was attenuated and the tumor infiltration by dendritic cells was enhanced with the addition of immunotherapy." (PMID 34063752, 2021). "The astrocyte-tumor interaction increases the expression of receptors for IL-6 and its subunit gp130 and decreases the receptors for TNF-α and IL-1β on HARA-B metastatic lung squamous carcinoma cells." (PMID 33466236, 2021). "Increased leptin, IL-8, IL-6, and IL-1β concentrations is reported in MDA-MB-231 and MDA-MB-468 cells after co-cultivation with adipocytes or adipocyte-conditioned medium favouring tumour cell survival and progression." (PMID 34812105, 2021). "Proinflammatory cytokine, IL-1β, activates endothelial cells to produce VEGF, which supports angiogenesis, contributing to tumor invasiveness and metastasis." (PMID 33919517, 2021). "The activation of the maternal immune system leads to an increase in the release of cytokines such as, IL-1β, IL-9, IL-17, Eotaxin-2 and IL2 in the tumor environment and subsequently in the maternal circulation." (PMID 34203890, 2021). "DC activation by binding to ATP also promotes caspase-1 dependent NLRP3 inflammasome formation and the release of IL-1β, which in turn promotes CD8+ T cells and IL-17 producing-γδ T cell mediated anti-tumor response." (PMID 34263254, 2021). "In the tumour stroma‐derived EVs, enrichment of IL1A, IL1B, and SNAI1 was consistent with a more inflammatory stromal phenotype typically associated with disease." (PMID 34596356, 2021). "Based on genetic analysis, TAMs can produce various molecules, including VEGF, TNF-α, IL-1β, IL-8, platelet-derived growth factor (PDGF), thymidine phosphorylase, and MMPs that are involved in tumor angiogenesis." (PMID 33230600, 2021). "As shown in the boxplot, IL1B, MST1, GBP1, and NLRP3 were downregulated, and the other 35 PRGs were upregulated in tumor tissues." (PMID 34869364, 2021). "Preclinical evaluation has demonstrated that NLRP3 inflammasome mediated IL-1β and IL-18 release results in IFN-γ production and CD8+ T cell-dependent tumor regression." (PMID 33572196, 2021). "Cisplatin treatment had a profound immunological effect by significantly reducing the levels of the primary tumor cytokines B-cell activating factor (BAFF) and interleukin (IL)-1β compared to vehicle treatment." (PMID 33731699, 2021). "Pro-inflammatory cytokines such as IL-1α, IL-1β, IL-6, TNF-α were constitutively expressed in tumor microenvironment to facilitate carcinogenesis." (PMID 34379689, 2021). "Among the inflammatory mediators, cytokines IL-1α, IL-1β, IL-6, and IL-8 and chemokine CXCL10 were highly expressed, suggesting a function of CAFs in tumor-mediating inflammation." (PMID 34298873, 2021). "The expression of M1 macrophage markers iNOS, IL-1β, TNF-α and CD86 was increased, and the expression of M2 macrophage markers IL-10, Arg-1 and CD206 was reduced in the tumour tissues of tumour-bearing mice." (PMID 34726570, 2021). "The expression levels of tumor progression-related proteins (MMP9, PCNA, and IL-1β) and MDSCs' proliferation and activation-related proteins (COX2 and PDL1) were significantly downregulated." (PMID 34055197, 2021). "Upon combination therapy, we observed a significant increase in IL1α and IL1β protein levels in the TME, both correlating with tumor regression." (PMID 34446712, 2021). "Interleukin-1β (IL-1β) acts on CD8+ T cells and promotes their expansion and effector differentiation, but toxicity and undesired tumor-promoting side effects hamper efficient clinical application of this cytokine." (PMID 34772757, 2021). "Likewise, when we explored the effects of IL1β-silenced tumor cells on co-cultured NCFs, we could observe that cocultured fibroblasts lost the expression of inflammatory cytokines, as IL6, LIF or CCL2, while acquired markers of myofibroblasts (ACTA2, PDPN, MYH11, or CNN1)." (PMID 34066976, 2021).
tumor (continued). "IL-1β and TGF-β have crucial roles in CCL2-induced macrophage polarization and tumor-entrained neutrophil education, which weaken cytotoxic capacity and are also correlated with inflammation-induced immunosuppression." (PMID 34386431, 2021). "During tumor development, TH17 promoting chemokines and cytokines are expressed within the TME, such as CCL4, CCL17, CCL22, IL-1β, IL-6, IL-23, and TGF-β." (PMID 34012451, 2021). "Following continuous TNFα + IL-1β stimulation, the two TNBC cell types formed fewer cell-to-cell contacts, remained dissociated from each other and generated only small tumor cell aggregates." (PMID 34072893, 2021). "There is a significant decrease of CD8+/CD4+T cells ratio, NK cells, IL-2, and IFN-γ and a significant increase of T regs, IL-6, IL-1β, TNF-α, IL-10, and PGE2 in CUMS group, indicating the inhibition of immunity in the tumor microenvironment." (PMID 34422050, 2021). "There was an upregulation of IL-1b, Ltb, Tnf, and Cxcl2 in brain organoids with ZIKVBR and tumor cells indicating inflammatory signaling mediated by the TNF family." (PMID 34696533, 2021). "IL-1β and TNF-α, in particular, show a notable overlap of biological activity in cancer and promote tumor angiogenesis by inducing tumor cells to secrete VEGF via the IκB/TSC1/mTOR pathway." (PMID 33925400, 2021). "Our previous studies showed that myeloid cells secrete various cytokines, such as IL-1β and TNF-α, to promote tumor cell autophagy and angiogenesis and correlate with poor clinical outcome in HCC patients." (PMID 35070979, 2021). "During tumor inhibition, P2X7R’s cytotoxic activities were described in immune cells, especially dendritic cells, to release pro-inflammatory cytokines (IL-1β and IL-18) via an NLRP3-dependent pathway." (PMID 34268121, 2021). "In detail, these authors demonstrated, in 4T1 tumor-bearing BALB/c mice, that the combination of IL-1β (AF-401-NA) and anti-PD1 (RMP1-14) antibodies was able to induce the complete inhibition of tumor." (PMID 33840390, 2021). "In line with the observed changes in the heart and the liver, tumor-bearing mice had significantly increased renal expression of the pro-inflammatory cytokines IL-1α, IL-1β, TNF-α, and Mcp-1 compared to tumor-free mice." (PMID 34445729, 2021). "Here, we also demonstrated that propolis decreased the levels of proinflammatory mediators, including TNF-α, IL-1β, and IL-6, as well as NLRP3 inflammasome to improve the tumor inflammatory microenvironment." (PMID 33628847, 2021). "H&E staining revealed significant inflammatory cell infiltration and intramucosal tumor in the colon of the AOM/DSS group, and the mRNA levels of inflammatory cytokines (IL-1β, IL-6, and TNF-α) were significantly increased." (PMID 33708251, 2021). "Only SFV4-infected tumor cells consistently induced DCs to secrete Th1 cytokines (IFN-γ, IL-12, TNF-α), Th2 cytokines (IL-4, IL-13), proinflammatory cytokines (IL-6, IL-8, IL-1β,) and anti-inflammatory cytokine (IL-10)." (PMID 31969562, 2020). "Carmi and colleague found that the cross-talk between IL-1β and VEGF regulated the early angiogenic response, which procured a microenvironment suitable for angiogenesis and tumor development." (PMID 33322216, 2020). "They promote angiogenesis via VEGF, promote tumor development and metastasis through cathepsin G and ROS, induce chronic inflammation by releasing TNF-α, IL-1β, IL-6, and IL-12, and inhibit effector CD8+ T cells." (PMID 32499786, 2020). "In this context, IL-1β enhanced CD4+TCRβ+RORγt+ cells producing IL-17, which are responsible for slowing down tumor growth." (PMID 32635472, 2020). "Interleukin-1 beta (IL-1β), a potent driver of tumor progression, is highly expressed in metastatic NSCLC tumors and drives tumor growth, invasion, and metastasis." (PMID 32802118, 2020).
tumor (continued). "In our study, greater numbers of lung carcinoma tumors and larger tumors were found in PRDX4 Tg mice, accompanied by enhanced macrophage infiltration and the elevated expression of IL-1β and MMP9 in tumor microenvironment." (PMID 33456675, 2020). "For instance, the high levels of IL-1β, IL-6, and CXCL2 in the tumor microenvironment favor MDSC expansion." (PMID 32632113, 2020). "Proinflammatory pathways are upregulated in KRAS-dependent tumors, including increased production of the chemokines IL-1β, CCL7, and CCL2, as a result of crosstalk between KRAS-mutant tumor cells and host myeloid cells." (PMID 33335263, 2020). "Following tumor excision, IHC analysis was used to determine tumoral expression of apoptosis- and pyroptosis-related biomarkers, including NLRP3, IL-18, IL-1β, and caspase-1." (PMID 32209729, 2020). "This indicated that FLP ointment significantly decreased the expression of IL-6, IL-1β, and TNF-α in exosomes, serum, lung, and tumour tissues." (PMID 32308722, 2020). "Silencing of PDIA3 in GB cells resulted in reduced release by tumor cells of IL6 and COX2 and increased production of IL1β." (PMID 33153019, 2020). "The immune cell recruitment involves several inflammatory mediators, such as CCL2, S100A8/9, IL-1β, IL-5, GM-CSF and lipid-derived PGE2, which promote cancer-related inflammation, emergency myelopoiesis and tumor progression." (PMID 32823961, 2020). "This study examined cytokine levels and found that the levels of inflammation-related cytokines, such as IL-6, IL-1β, and TNF-α, were decreased in FLP-treated MO mice in the tumour tissues compared to those of MO mice." (PMID 32308722, 2020). "IL-1β seems to be required for secretion of Th1-derived cytokines IL-2 and IFN-γ at the tumor site, and subsequent blockade of B-cell myeloma and lymphoma growth." (PMID 32635472, 2020). "IL-1β improves the antitumor effect of ATCT, which correlates with stronger infiltration of CD8+ T cells in the tumor, a more pronounced effector phenotype and enhanced peripheral survival." (PMID 33584721, 2020). "It has been reported that tumor-derived IL-1β enhances MDSCs infiltration, accumulation, and immunosuppressive activity within the TME, thereby promoting tumor progression." (PMID 31941522, 2020). "In order to provide further insights into the metastatic gene expression profile triggered by hypoxia through the IL-1β/IL1R1 axis, we performed a TaqMan Gene Expression Assay, which consists of a Human Tumor Metastasis Array." (PMID 32778144, 2020). "IL‐1β can infiltrate and promote angiogenesis in solid tumours, and the mitogen‐activated protein kinase (MAPK) pathway also plays a principle role in tumour angiogenesis." (PMID 32239650, 2020). "Increased protein expression of caspase-1, IL1β, and IL18 occurred in surface epithelium, tumor cells, and immune cells." (PMID 31923221, 2020). "Products of inflammasome activation (IL-1β and IL-18) behave as protumorigenic factors in gastrointestinal cancers, while the protective role of NLRP6 against tumor development has been clarified, whereas, for NLRC4, contrasting findings were reported." (PMID 32796686, 2020). "To investigate the influence of exogenous IL-33 on pro-inflammatory factors, such as IL-6, IL-1β, and tumour necrosis factor (TNF)-α, we measured their mRNA expressions, which are known to stimulate tumour proliferation and angiogenesis." (PMID 33308251, 2020). "Expectedly, IL1B expression was enhanced in blood monocytes isolated from RCC patients and in tumor tissue." (PMID 32630814, 2020). "Then, this IL-1β is able to trigger CAFs to release thymic stromal lymphopoietin (TSLP), which is a key cytokine for Th2 pro-tumor immune response." (PMID 32635472, 2020). "The early steps of PI seem to be controlled by IL-1β and macrophages in establishing a metastatic niche, whereas in presence of the tumor and MDSC cells in a later metastatic phase support tumor expansion." (PMID 31685946, 2020).